EGF (epidermal growth factor)
Diseases named in the same sentence as EGF in open-access papers (continued):
Sharing a sentence is not in itself a finding about the gene and the disease.
tumor (continued). "Intravital imaging in tumor-bearing mice showed that dextran-labeled TAMs expressing CSF-1 receptor and GFP-labeled tumor cells expressing EGF receptor co-migrated toward microneedles containing either EGF or CSF-1." (PMID 29599778, 2018). "Epidermal growth factor (EGF)-mediated glycosylation inactivates GSK3β, while TNF-α induces COP9 signalosome 5 (CSN5)-mediated deubiquitination, both of which lead to stabilization of PD-L1protein in tumor cells." (PMID 29580288, 2018). "Because basal levels of PD-L1 are almost undetectable in SKBR3 cells, and are unchanged following EGF or IFNγ treatment, we used mouse KPB6 tumor cells, which show a robust PD-L1 response to IFNγ, as an alternative model to confirm the PD-L1 surface expression phenotype." (PMID 30021161, 2018). "In our study neither EGF nor EGFR expression did differentiate metastasis from primary tumour, which suggests there is other mode of MMP activation." (PMID 30231850, 2018). "Growth signals from the tumor stroma, such as TGF-β (transforming growth factor), EGF (epidermal growth factor), FGF (fibroblast growth factor), PDGF (platelet-derived growth factor), IGF (insulin growth factor) and HGF (hepatocyte growth factor), are responsible for triggering EMT in cancer cells." (PMID 29416704, 2018). "Induction of EMT through EGF/EGFR/ERK1/2 entailed functional consequences, as cells were equipped with enhanced migration capacity and might thereby impact local and distant tumor cell dissemination." (PMID 30261040, 2018). "In addition, growth factors that are widely used as wound healing agents, including EGF and PDGF20,21, have not only disadvantages such as large-scale production cost, but also reports of adverse effects such as tumour formation." (PMID 30258088, 2018). "In particular, transforming growth factor-β (TGF-β), platelet-derived growth factor (PDGF), epidermal growth factor (EGF), and fibroblast growth factor (FGF) secreted by tumor cells are key determinants of fibroblast activation and proliferation within the TME." (PMID 29545811, 2018). "The initial tumor microenvironment established by Matrigel involves a low-pressure, semiliquid milieu that is rich in collagen, heparin sulfate and growth factors, including tissue growth factor beta (TGF-β) and epidermal growth factor (EGF)." (PMID 29903803, 2018). "SWCNT-Qdot-EGF conjugates injected into live mice were selectively taken up by HNSCC tumors but SWCNT-Qdot controls with no EGF were cleared from the tumor region in <20 min." (PMID 30347840, 2018). "Five aberrantly methylated genes (epidermal growth factor, EGF; carbohydrate sulfotransferase 10, CHST10; ependymin related 1, EPDR1; bone marrow stromal antigen 2, BST2; and Rac family small GTPase 3, RAC3) were further verified in CRC tumor tissues." (PMID 30360391, 2018). "From SOM to EOT, e.g. during tumor progression on single bevacizumab treatment, weak evidence was observed for increase in the level of five proteins (TIMP-4, MMP-8, EGF, Amphiregulin, and Tissue factor/Coagulation factor III), whereas a decrease was seen in only one protein (CD26)." (PMID 30592740, 2018). "Importantly because external stimuli (Ca2+ and EGF) can modulate the effects of CASP4, the microenvironment can influences CASP4-mediated cellular events including tumor development." (PMID 30531914, 2018). "Furthermore, increased levels of epidermal growth factor (EGF), insulin growth factor-1 (IGF1) and lysophophatidic acid (LPA) have been shown to promote tumor cell pro-migratory effects." (PMID 29416793, 2018). "Stimulation of the DK-MGhigh or primary tumor cells with EGF did not result in elevated phosphorylation of the mutant receptor, despite the marked increase in phosphorylation of the wild-type EGFR, which is in contrast to previous reports." (PMID 29492217, 2018). "This uptake was enhanced by HGF or EGF (not shown), suggesting GF induction of endocytic activity in the tumor cells." (PMID 29796184, 2018).
tumor (continued). "In particular, CAFs differentiation can be induced by tumour cell-derived transforming growth factor β (TGF-β), epidermal growth factor (EGF), PDGFα, PDGFβ, basic fibroblast growth factor (bFGF, also known as FGF2), interleukin 6 (IL-6), and interleukin 1β (IL-1β)." (PMID 29967776, 2018). "TAMs produce the higher level of cytokines, TGFα, EGF, FGF and VEGF in the tumor microenvironment." (PMID 29455658, 2018). "The EGF binds to epidermal growth factor receptor (EGFR) to induce the expression of VEGF-A by triggering downstream Ras-MAPK, PI3K-Akt, and STAT signaling pathways, which play important roles in tumor growth and dissemination." (PMID 28486560, 2017). "Interestingly, tumor microenvironment produces cytokines, chemokines and growth factors, including TNFα, TGFβ, IL-6, FGF, epidermal growth factor (EGF), and HGF." (PMID 29088851, 2017). "Conversely, FGF, EGF, and HGF can influence tumor cells in both autocrine and paracrine fashions." (PMID 27965469, 2017). "The expression of cytokine epidermal growth factor, CXCL9, CCL25, and MMP9 were differently expressed between primary tumor and metastasis sites, especially when cocultured with MSCs, suggesting a crosstalk between MSCs and tumor cells." (PMID 28205428, 2017). "Compounds No.39 and No.94 have been studied for many years as tumor inhibitors by targeting tyrosine kinase, an EGF (epidermal growth factor) receptor." (PMID 29209282, 2017). "Of note, Spry was shown to be an important negative regulator of protumorigenic fibroblast growth factor (FGF) and epidermal growth factor (EGF) signaling pathways, underscoring the importance of this molecule and the newly identified mechanism in tumor suppression." (PMID 28275056, 2017). "We next examined the effects of SWT on EGF-mediated neoplastic transformation of the mouse epidermal JB6 P+ cell line, which is a well-characterized model for studying cellular response to various tumor promoters." (PMID 28335476, 2017). "On the other hand, this let us assume that a monotherapy with HisDianthin‐EGF is not sufficient to kill tumor cells with lower EGFR expression resulting in selective survival of these cells and continuous tumor growth." (PMID 28755527, 2017). "Uptake was 3.9% versus 2.8% injected dose/g (%ID/g) of tumour tissue with and without unlabelled EGF, respectively." (PMID 29071190, 2017). "Here, we show that EGF up-regulates CCR1 expression, suggesting that CCR1 may contribute to EGFR-mediated tumor invasion and metastasis." (PMID 29212252, 2017). "In vivo imaging with MRI- fluorescence molecular tomography (MRI-FMT) of mice injected with IRDye 8000CW labeled EGF, showed a 100% sensitivity and specificity in distinguishing mice with EGFR (+) tumor cell lines from EGRF (−) tumor cell lines or control mice." (PMID 27878374, 2017). "Pre-treatment with epidermal growth factor (EGF) at a low dose promoted the lung metastasis of 4T1 cells without significantly altering primary tumour growth under the nipple; this effect on metastasis was further promoted by FAF1 depletion." (PMID 28443643, 2017). "Some signals received from tumor microenvironments, such as tumor necrosis factor α (TNFα), transforming growth factor β (TGFβ), IL-6, fibroblast growth factor (FGF) and epidermal growth factor (EGF), can trigger EMT." (PMID 28060811, 2017). "Tumor cell invasion also appears to recapitulate some aspects of the liver wounding response triggering HSC activation, ECM deposition and the release of growth factors such as TGF-β, EGF, VEGF and IGF-I." (PMID 28881729, 2017). "JAKs are key participants in signaling networks fueled by a variety of cytokine and growth factor receptors in the tumor microenvironment, including IL-6, IL-11, IL-27, interferon (IFN-α/β/γ) oncostatin M (OSM), leukemia inhibitory factor (LIF), epidermal growth factor (EGF) and others." (PMID 29190997, 2017).
tumor (continued). "Based on the vital role of NF-κB signals and MIIP in tumor metastasis, we first examined whether MIIP is involved in the EGF-induced NF-κB activation." (PMID 29038521, 2017). "Interestingly, recent evidences have demonstrated an important role of EGF/EGFR signaling in inducing epithelial-mesenchymal transition and thereby promoting cell motility in epithelial cells from several tumor types." (PMID 28430640, 2017). "The Boyden chamber assay revealed that tumor cells do not migrate without a chemoattractant but can be highly mobilized by EGF." (PMID 28008153, 2017). "Another example of the crosstalk between c-MYC and growth factors are double transgenic mice expressing epidermal growth factor (EGF) and c-MYC, in which exacerbated tumor progression and mortality led to the occurrence of HCC in 100% of the mice after approximately 12–18 weeks." (PMID 28422055, 2017). "We found that under the stimulation of EGF, the RAS–MAPK pathway could activate ATXN1, which plays an important role in tumor growth." (PMID 29212253, 2017). "Components of the epidermal growth factor (EGF) pathway, the α subunit of the G protein Gs, retinoic acid protein 3, and resistin are over-represented in uEVs of patients and potentially involved in tumor progression." (PMID 28638822, 2017). "Tumor cells or tumor micro-environment promotes angiogenesis through the induction of various cytokines or growth factors such as vascular endothelial growth factor (VEGF), angiopoietin, basic fibroblast growth factor (bFGF) and epidermal growth factor (EGF)." (PMID 27517319, 2016). "EGF through EGFR/ERBB1 activates various downstream signaling pathways which in turn trigger other transcription factors and co-activators that can affect the proliferation of tumor cells." (PMID 27564112, 2016). "Additionally, epidermal growth factor, an important ligand for EGFR, also drives VEGF expression, and an overactive VEGF pathway plays a role in tumor resistance to treatment with EGFR inhibitors." (PMID 27245053, 2016). "We therefore evaluated whether EGFR, ASAP1, ERBB2 and ERBB4, which signal downstream after ligation of EGF, and which show aberrant expression in several other invasive cancers, would also predict HBL tumor invasiveness." (PMID 27910913, 2016). "The presence of IL-17E in the TNBC tumor microenvironment may pre-activate the EGFR via Src/PYK2 crosstalk, thus resulting in enhanced sensitivity to EGF and potentially other EGFR ligands." (PMID 27462789, 2016). "Although mutations of the PTP1B gene have not been linked to cancer and despite the fact that PTP1B regulates the activity of both the epidermal growth factor (EGF) and the platelet-derived growth factor (PDGF) receptors, the enzyme is considered a tumor suppressor." (PMID 27890939, 2016). "Stimulated by growth factors EGF and HGF respectively, EGFR/Ras/Raf/MEK/ERK and HGFR/PI3K/AKT pathways converge to phosphorylate BAD that plays a critical anti-apoptotic role in many types of tumor cells." (PMID 27590512, 2016). "Additionally, the vascular endothelial growth factor A (VEGF-A) and its receptor VEGFR-1/2 were interacted to affect to tube formation of tumor cells by TGF-β1, at same time, EGF/EGFR also has similar activity." (PMID 27613831, 2016). "In conclusion, we speculate that EGF-induced expression and activity of COX-2 and fibronectin promotes tumor metastasis by modulating adhesion between tumor and endothelial cells." (PMID 25595899, 2015). "Epithelial-mesenchymal transition (EMT), a process closely related to tumor development, is regulated by a variety of signaling pathways and growth factors, such as transforming growth factor-β1 (TGF-β1) and epidermal growth factor (EGF)." (PMID 26005723, 2015).
tumor (continued). "A number of miRNAs regulate the EGF signalling pathway, for instance MIR-145 can act as a tumour suppressor and down regulates several crucial oncogenes such as ki-RAS and v-myc, it is also down regulated in various types of cancer and has been shown to induce apoptosis." (PMID 25781916, 2015). "Tumor cell migration and invasion are dependent on epithelial cells increasing their ability to migrate through a process named EMT, and EMT is strongly induced by EGF signaling in PCa and other cancer types." (PMID 25915156, 2015). "Furthermore, these cells have increased exposure to the factors necessary for tumor relapse, including CXCL12, through its receptors CXCR4 and CXCR7, IL6 through the Jak2/Stat3 pathway, EGF, FGF and IGF, among others." (PMID 25797268, 2015). "A cocktail of well characterized tumor growth factors (EGF, HGF, and IGF-1) were analyzed in parallel as a positive control to determine whether freshly-isolated tumor cells were able to respond to growth factor activation ex vivo." (PMID 25807104, 2015). "Furthermore, factors physiologically released by bronchial epithelium such as TGF-β, epidermal growth factor (EGF) and bombesin contribute to tumour growth 90–93." (PMID 25598217, 2015). "In an in vivo metastasis assay, lung metastasis following tail vein injection of EGF-treated tumor cells was significantly increased in the parental but not the shCOX-2 cells." (PMID 25595899, 2015). "EGFR receptors include AR, EGF, TGF-α, epiregulin, heparin-binding EGF (HB-EGF) and Hepatocarcinoma cell-derived hepatoma-derived growth factor (HDGF), have been confirmed to mediate tumorigenesis and promote tumor progression." (PMID 26451607, 2015). "In our previous study several immunoglobulins were found to be either repressed or absent in serum of EGF tumour bearing mice and this was particularly obvious for the Ig K and L classes." (PMID 25872475, 2015). "Together these results indicate that the native tumour-stromal micro-architecture and phenotypic features were largely conserved in the CANScript tumour ecosystem compared with the culture conditions with only TMP or AS or EGF-supplemented TMP." (PMID 25721094, 2015). "In addition to driving TNBC tumor formation, BRCA1-IRIS overexpression drives their intrinsic and acquired paclitaxel resistance, partly by activating autocrine signaling loops EGF/EGFR-ErbB2 and NRG1/ErbB2-ErbB3." (PMID 25583261, 2015). "Collectively, these data suggest that under hypoxic conditions, HIF-1β expression regulates the expression of tumor growth-related factors, namely EGF and HGF, but not FGF2." (PMID 25068796, 2014). "It is possible that the release of EGF and many other RTK ligands (e.g., VEGF, bFGF, HGF) is induced as a consequence of TNFα activation, leading to RTK activation and then to cooperation in the release of CXCL8 by the tumor cells." (PMID 24598028, 2014). "For example, a study on the saliva of OSCC patients demonstrated raised EGF levels post-surgery, which may indicate OSCC regeneration secondary to tumour tissue injury thus implying a role of EGF in the development of OSCC." (PMID 25866477, 2014). "Increased hepatocyte growth factor (HGF) and epidermal growth factor (EGF) levels may be an additional explanation for the accelerated tumor growth due to the stimulatory effects that HGF and EGF exhibit on tumor cells." (PMID 24940392, 2014). "Collectively, these results demonstrate that under hypoxic conditions, HIF-1β expression regulates the expression of various tumor growth-related factors, namely EGF, HGF, and VEGF, but not FGF2." (PMID 25068796, 2014). "Moreover, EGF is one of the growth factors that lead to VEGF and MMP-9 expression, crucial mediators for tumor angiogenesis and invasion in the RCC microenvironment, therefore facilitating the spread of tumor cells." (PMID 25909813, 2014).
tumor (continued). "Notably, PHD3-silenced tumour cells exhibited a striking and prolonged increase in EGFR phosphorylation under basal conditions as well as after EGF stimulation for 5 and 15 min." (PMID 25420773, 2014). "In PC there is an abnormally high expression of a number of important tyrosine kinase growth factors and receptors, like the Epidermal Growth Factor (EGF) family, which may contribute to the neoplasia growth by autocrine and paracrine effects." (PMID 25510623, 2014). "EGF and its receptor EGFR serve as a paradigm for signaling in cell, molecular and tumor biology." (PMID 25184905, 2014). "A negligible mRNA expression level was detected for EGF in both tumor and normal tissue, and therefore this ligand was not considered for further analysis." (PMID 24728052, 2014). "These various cell populations with or without stem phenotypes were analyzed for tumor sphere formation in serum free medium supplemented with bFGF and EGF." (PMID 24265713, 2013). "Interestingly, we found that the chemoinvasive behavior to SDF-1α gradients was abrogated or even reversed in the presence of uniform concentrations of EGF; however, the presence of SDF-1α and EGF together modulated tumor cell motility cooperatively." (PMID 23869217, 2013). "Insulin, angiotensin-II and epidermal growth factor have been shown to up-regulate HIF in the presence of molecular oxygen and mTOR inhibition decreases tumour progression partially to decreased neo-vascularisation, indicating mTOR as a regulator of HIF by increasing its mRNA translation." (PMID 23758895, 2013). "BM-derived MSC have also been shown to migrate toward tumor hypoxia-induced secretion of growth factors (VEGF, PDGF, EGF) in pancreatic tumors, and contribute to neovascularization by homing to fast growing tumors and incorporating into blood vessels as atypical VEGF-secreting endothelial cells." (PMID 23531764, 2013). "Contrary to PDGF, EGF cannot initiate malignant transformation and results with EGF in experimental models have not demonstrated tumor promotion consistently." (PMID 24004460, 2013). "On the other hand, when subjected to EGF gradients alone, tumor cells increased their overall motility, but without statistically significant chemotactic (directed) migration, in contrast to previous reports using 2D chemotaxis assays." (PMID 23869217, 2013). "Mice injected with EGF imaging agent showed higher signal intensity in the MDA-MB-468 tumor than the receptor-negative MDA-MB-435 tumor." (PMID 23331017, 2013). "The ability of DOK2 to inhibit EGF-induced activity of wild-type RAS and the fact that DOK2 is constitutively bound to RASA1 in cells harboring EGFRL858R suggest that at least part of DOK2’s tumor suppressive function is to suppress RAS activation via RASA1." (PMID 24255704, 2013). "Carcinoma cells and HaCaT cells were treated with tumor stimulus, TGF-β, TNF-α or EGF." (PMID 23936352, 2013). "Taken together, the results show that this comparatively simple procedure is suitable to precisely measure specific short-term effects of EGF on cell motility and to distinguish between EGF-responding and non-responding tumor cells." (PMID 23028903, 2012). "EGF treatment significantly enhanced pulmonary metastasis of FG cells expressing a control shRNA as expected, but shRNA-mediated knockdown of MUC1 expression selectively blocked EGF-induced pulmonary metastasis without preventing primary tumor growth." (PMID 22586492, 2012). "Because there is an EGF-CSF-1R paracrine loop with macrophages inducing tumor cell invasion, we tested whether CXCL12 would act on the Neu-YB tumor cells to increase invasion in an autocrine manner or in a paracrine loop with macrophages." (PMID 22314082, 2012).